RACK1 (receptor for activated C kinase 1)
Diseases named in the same sentence as RACK1 in open-access papers (continued):
Sharing a sentence is not in itself a finding about the gene and the disease.
tumor (97 papers, 2008 to 2026). "Period circadian regulator 1 (PER1) mutations enhance glycolytic flux and tumor progression via the receptor for activated C kinase 1 (RACK1)/PI3K/AKT pathway." (PMID 40725147, 2025). "Our results indicated that the overexpression of circVPRBP led to the inhibition in tumor growth, while the Dox-induced RACK1 reversed the inhibition of tumor growth caused by the overexpression of circVPRBP." (PMID 36658304, 2023). "Tyrosine (de)phosphorylating activity is a prerequisite for the proper activity of RACK1 in animal models, where RACK1 deregulation is often associated with tumor progression." (PMID 36768198, 2023). "In this study, we found that the expression of Rack1 was significantly upregulated in the majority of MB tumor samples, suggesting the pathogenic potential of Rack1 in MB development." (PMID 34480519, 2021). "RACK1 is capable of upregulating the expression of a series of miRNAs, including the miR-302 cluster, and its loss promotes GC tumor invasion and metastasis through miR-302c suppression." (PMID 32792866, 2020). "Overexpression of RACK1 served as a biomarker associated with increased pathological stage, tumor size, and lymph node involvement in pulmonary adenocarcinoma in a recent study." (PMID 28465488, 2017). "In pulmonary adenocarcinomas, increased RACK1 expression is associated with pathological stage and tumor size and is also a potential diagnostic marker." (PMID 21978545, 2011). "Interestingly, similar to the present study, it has been shown that O‐GlcNAcylation modification of RACK1 is associated with tumour progression." (PMID 38451046, 2024). "Furthermore, the elevated O-GlcNAcylation of RACK1 was associated with tumor progression and increased recurrence rates following chemotherapy in patients with HCC." (PMID 39199296, 2024). "Moreover, RACK1 also regulates the stability of some key tumor-associated proteins through the ubiquitin-proteasome system (UPS)." (PMID 37848434, 2023). "Next, we asked whether Rack1 deficiency could induce the cell apoptosis of MB tumor cells, which may also contribute to the tumor suppression effect in rescue mice." (PMID 34480519, 2021). "Our results showed a significant reduction in proliferation of MB tumor cells with Rack1 deficiency specifically in GNPs in vivo, suggesting the effect of Rack1 deletion on MB tumor proliferation might be cell autonomous." (PMID 34480519, 2021). "Interestingly, RACK1 is also associated with tumour immunotherapy." (PMID 38451046, 2024). "Crucially, combined targeting of RACK1 with c-Src or LDHA inhibition yielded synergistic anti-tumor effects in vivo, significantly surpassing monotherapies." (PMID 42215440, 2026). "A stringent cross-comparison identified five proteins (PSAP, MARCKS, eEF1A1, DDX39B, and RACK1) as consistently and differentially regulated across tumor stages." (PMID 42064067, 2026). "RACK1 supports tumor development by inducing autophagy in colon cancer cells, promoting proliferation, and inhibiting apoptosis." (PMID 40917756, 2025). "The FAK/RACK1/PDE4D5/Rap1 axis facilitates tumor cell adhesion and migration through localized cAMP degradation." (PMID 41179677, 2025). "Our spatially resolved analysis indicated that RACK1 aligns with oleic acid and genes related to lipid synthesis within the tumor region." (PMID 39425259, 2025). "As a multifunctional scaffold protein, RACK1 can bind to a variety of proteins in the cell, regulate protein activity, and affect the growth and differentiation of tumor cells." (PMID 39425259, 2025). "This upregulation of RACK1 is positively correlated with tumor grading, suggesting its involvement in tumorigenesis." (PMID 40060229, 2025). "RACK1 affects various behaviors such as cell cycle, cell proliferation, migration and invasion, epithelial mesenchymal transition, and tumor cell differentiation via these signal pathways." (PMID 38398158, 2024).
tumor (continued). "RACK1, a scaffold protein for kinases and receptors, has multiple biological functions, including signal transduction, tumor cell invasion, angiogenesis, and immune responses." (PMID 39334337, 2024). "To validate the potential key role of RACK1 in OTUB1-mediated tumor suppression, we performed the exogenous Co-IP assay first." (PMID 38315284, 2024). "Our findings suggest that SBSGL is a potential agent for tumour immunotherapy and modulates the malignancy and autophagy of HB by regulating the O‐GlcNAcylation of RACK1." (PMID 38451046, 2024). "Cao and coworkers reported that RACK1 stabilized Nanog activity and enhanced tumor cell self-renewal and chemoresistance in HCC." (PMID 39199296, 2024). "Western blotting showed that RACK1 was expressed in four tumor cells with the correct molecular weight." (PMID 39458945, 2024). "Eliminating the O-GlcNAcylation of RACK1 at Ser122 markedly inhibited tumor growth, angiogenesis, and metastasis." (PMID 39199296, 2024). "In HCC, RACK1 was found to promote tumor growth and chemoresistance through the promotion of eIF4E phosphorylation." (PMID 39199296, 2024). "In HNSCC, M2-like polarization is thought to be driven by the receptor for activated C kinase 1 via NF-κB suppression to promote tumor development." (PMID 39630300, 2024). "Our findings provided evidence of how PCa cell-derived exosomal PSM-E suppressed tumor metastasis by modulating the RACK1/FAK/ERK signaling pathway." (PMID 39538297, 2024). "It has been shown that RACK1 is closely related to tumor progression due to its modulation of multiple signaling pathways including PKC, receptor tyrosine kinase/PI3K/AKT, ERK/MAPK, STAT3, Src/FAK, NF-κB, Wnt/β-catenin, and RhoA/Rho pathway." (PMID 38398158, 2024). "We investigated OTUB1 functioned as a tumor promoter in HCC through the deubiquitination of RACK1, which subsequently activated the downstream PI3K/AKT and FAK/ERK signaling pathway." (PMID 38315284, 2024). "Specifically, abnormally low expression of the E3 ligase SMURF2 led to a decrease in the SMURF2-RACK1 complex, resulting in decreased ubiquitination of RACK1 and increased stability, which promoted tumor progression." (PMID 37828084, 2023). "Isolation of the receptor for activated C kinase-1 (RACK1)—a known pro-apoptotic factor—within SGs inhibits tumor cell apoptosis." (PMID 37179344, 2023). "Tumor growth was very slow in the RACK1-silenced group compared with the control and RACK1-rescued groups." (PMID 37848434, 2023). "Previous studies have shown that RACK1 regulates tumor metastasis by either promoting or inhibiting the progression of different tumor types and by regulating their microenvironments." (PMID 35957886, 2022). "Translation control of specific genes mediated by MYCT1/RACK1 provides a precise means to fine-tune glycogen shunt assisting tumor cells to achieve metabolic homeostasis." (PMID 35281731, 2022). "As RACK1 is a crucial factor in tumour progression and development, we sought to investigate its role in NSCLC and its relation with CPNE1, as well as the underlying mechanism." (PMID 35101055, 2022). "Taken together, these observations indicated that aberrant regulation of RACK1 expression can affect tumour progression through promoting MET signaling in NSCLC." (PMID 35101055, 2022). "The translational upregulation of PGM1, UGP2 and GSK3A mediated by MYCT1 and RACK1 adjusted the flux of glycogen synthesis and glycogen shunt, which is crucial for modulating the tumor metabolic reprogramming." (PMID 35281731, 2022). "To study the beneficial effect of Rack1 deletion on MB tumor therapy, we further compared the survival curve between different genotypes." (PMID 34480519, 2021). "Our major finding in the present study is that PHB2 facilitates tumorigenesis in NSCLC by interacting and stabilizing RACK1, which further induces changes in downstream tumor effectors and pathways." (PMID 33537079, 2021).
tumor (continued). "In this study, the Rack1‐deleted SHH‐MB rescue mice provide a useful model with which to directly test the tumor suppression effects on SHH‐MB development." (PMID 34480519, 2021). "To address this issue, we first examined the expression of Rack1 in a paraffin‐embedded MB tumor tissue organized row from 20 patients and a normal cerebellum control by immunohistochemistry staining." (PMID 34480519, 2021). "Tumour-derived IL-8 can promote metastasis when receptor for activated C-kinase 1 (RACK1) is dysregulated, highlighting IL-8’s potential for worsened prognosis." (PMID 34944729, 2021). "To further investigate how Rack1 deletion causes the inhibition of SHH‐MB tumor formation, we compared the proliferation and cell death of SHH‐MB tumor cells in vivo." (PMID 34480519, 2021). "Previous studies demonstrate that Rack1 has a dual role in regulating tumor cell proliferation, apoptosis, and metastasis." (PMID 34480519, 2021). "According to previous studies, an increased level of RACK1 indicates a poor clinical outcome and tumor progression in patients with OSCC." (PMID 31997535, 2020). "Here, we investigated the impact of RACK1 OSCC expression on the recruitment and differentiation of tumor‐associated macrophages." (PMID 31997535, 2020). "Ribosomal receptor for activated C-kinase 1 (RACK1) is associated with chemoresistance and tumour growth, with increased levels of RACK1 correlating with tumour progression and fatality." (PMID 33375613, 2020). "A series of experiments were conducted to evaluate the effects of the RACK1/miR-302b/c/d-3p-CCNO axis in CSCC cell progression as well as tumor growth." (PMID 32792866, 2020). "The results were also supported by tissue microarray staining data: RACK1 expression in tumor tissues was significantly higher than that in benign lesions and normal skin tissues." (PMID 31949482, 2020). "High RACK1 expression in OSCC cells correlated with increased M2 macrophage infiltration in tumor samples from a clinical cohort study." (PMID 31997535, 2020). "In terms of RCC specific signaling pathways deregulation it was previously reported that receptor for activated C kinase 1 (RACK1) is a direct mediator between loss of pVHL function and IGF1R signaling in RCC tumor cells." (PMID 30929166, 2019). "Three months after injection, apparent reduction of tumor metastatic foci was shown in the lung surface of Rack1-silenced group compared with the control group." (PMID 31113450, 2019). "The size and the number of tumor foci in the lung were significantly decreased in Rack1-silenced group compared with those in the control group." (PMID 31113450, 2019). "Scholars have formed a common belief that that RACK1 plays a major role in regulating some important biology process such as cell multiplication, neural system development, metabolism, tumor metastasis, and invasion." (PMID 30460084, 2018). "Hakai-mediated down-regulation of E-cadherin is involved in oncogenic and/or tumor-suppressive signaling pathways such as RACK1 and Slit-Robo signaling during tumor progression." (PMID 30041665, 2018). "RACK1 (Receptor for Activated C Kinase 1) is a ribosomal protein that contributes to tumor progression by affecting proliferation, apoptosis, angiogenesis, and migration." (PMID 26893362, 2016). "With regard to its roles in tumorigenesis, RACK1 mainly contributes to tumor growth, invasion and metastasis." (PMID 27170279, 2016). "Guanine nucleotide binding protein (G protein), beta polypeptide 2-like 1 (GNB2L1), which is also known as RACK1, encodes a ubiquitously expressed scaffolding protein and plays a crucial regulatory role in tumor growth." (PMID 23497483, 2013). "Subtle changes in the protein expression (both up and down) of a fundamental protein such as RACK1 can be expected to have dramatic consequences on the regulation of these key pathways and therefore on the development and progression of neoplastic disease." (PMID 21978545, 2011).
tumor (continued). "Syntaxin 6 induced tumour progression through an adaptor, RACK1, which recruited STAT3." (PMID 40293576, 2025). "In addition, RACK1 can regulate its function through interactions with several key proteins, thus affecting the occurrence and development of various tumours." (PMID 41190648, 2025). "However, the tumor metabolic microenvironment is governed by a complex regulatory network, and further research is needed to elucidate the precise mechanisms by which RACK1 modulates molecular pathways in lipid metabolism." (PMID 39425259, 2025). "Additionally, for breast cancer it was recently shown that abundant RACK1 mediates the tumor growth in vitro and in vivo due to its involvement in the WNT pathway and β-catenin." (PMID 41369326, 2025). "Moreover, the kinase RACK1 plays a key role in colonic epithelial carcinogenesis, and its expression gradually increases, positively correlating with tumor aggressiveness and, inversely, with patient survival." (PMID 40917756, 2025). "Currently, accumulating evidence indicated RACK1 could regulate tumor immunity by influencing the massive recruitment of macrophages and secretion of proinflammatory cytokines." (PMID 38315284, 2024). "Notably, several studies have shown that the level of RACK1 expression is positively correlated with the proliferation, growth, infiltration, and invasion of many kinds of tumor cells." (PMID 38831394, 2024). "Therefore, in order to detect the content of RACK1 in tumor tissues, we conducted RT-qPCR and western blot method." (PMID 39251538, 2024). "The function of RACK1 in tumor progression is tissue specific in different biological contexts." (PMID 37828084, 2023). "Moreover, the GEPIA and TNMplot databases showed that RACK1 expression was significantly higher in GC tissues than in non-tumor tissues." (PMID 37707957, 2023). "Since we have investigated the suppressive role of circVPRBP on tumor growth before, we pursued an in vivo subcutaneous xenograft model to see whether RACK1 was important for the potent anti-proliferative role of circVPRBP in CCa cells." (PMID 36658304, 2023). "For example, RACK1 inhibits the recruitment of macrophages and regulates the differentiation of macrophages into the M2 macrophages, leading to an anti-inflammatory response, which promotes the development of tumours." (PMID 37684678, 2023). "Meanwhile, the emergence of RUNX1 mutation, upregulations of genes expression (RPS27A, RPS6, UBA52, RACK1) on tumor cells, and increased frequencies of T and NK cells with TIGIT, CTLA4, and LAG3 expression were observed after midostaurin treatment, predicting the disease progression of this patient." (PMID 37638009, 2023). "RACK1 is known to play an important but dual role in tumour progression." (PMID 35101055, 2022). "RACK1 was found to be downregulated and act as a tumor suppressor in gastric cancer." (PMID 33537079, 2021). "According to previous studies, Rack1 has close relevance to tumor formation." (PMID 34480519, 2021). "Here, we found that Rack1 was significantly upregulated in some cerebellar MB tumor samples." (PMID 34480519, 2021). "Together, these results indicated that suppression of Rack1 expression in GNPs could significantly inhibit SHH‐MB tumor growth and increased the survival rate of rescued mice." (PMID 34480519, 2021). "Similar results were observed by Ki67 immunofluorescent staining in SHH‐MB tumor and rescue mice models at P30, further indicating that deletion of Rack1 could significantly suppress the proliferation of SHH‐MB tumor cells." (PMID 34480519, 2021). "Subsequently, using a SHH‐MB genetic mouse model, Atoh1‐Cre; SmoM2+/−, we demonstrated that ablation of Rack1 could significantly inhibit the growth of tumor cells with a dramatically extended lifespan in rescue mice." (PMID 34480519, 2021). "We propose that Rack1‐mediated Gli1 signaling and cell cycle activation in MB tumor cells might be essential for SHH‐MB tumorigenesis." (PMID 34480519, 2021).
tumor (continued). "To further explore whether PHB2 promotes tumor progression by regulating RACK1, we depleted endogenous RACK1 in PHB2-overexpressing A549 cells." (PMID 33537079, 2021). "However, the effect of RACK1 on the tumor immunological microenvironment in OSCCs is poorly understood." (PMID 31997535, 2020). "Receptor for activated protein kinase C (RACK1), a multifunctional scaffolding protein, plays a functional role in nucleating cell signaling hubs and regulating protein activity, and is also involved the modulation of migration and invasion of tumor cells." (PMID 32792866, 2020). "RACK1 may act via a variety of processes in tumours, including upregulating the assembly and activity of the NLRP3 inflammasome, miRNAs patterning, and AhR regulation." (PMID 33375613, 2020). "Furthermore, tumor xenograft in nude mice exhibited a pronounced decline in size, volume and weight of subcutaneous tumors in nude mice after overexpression of RACK1." (PMID 32792866, 2020). "The O-GlcNAcylation of RACK1 may therefore modulate the melatonergic pathway in the tumour microenvironment via both YY1 and NLRP3." (PMID 33375613, 2020). "Finally, RAB40C protein regulates, via an ubiquitin-proteasome system, the degradation of RACK1 protein, which is important in tumour growth and T-cell migration." (PMID 32707447, 2020). "Since RACK1 is a relevant EDCs target that responds to steroid-active compounds, it could be considered a molecular bridge between the endocrine-regulated tumour microenvironment and the innate immune system." (PMID 33287384, 2020). "Indeed, changes in RACK1 levels are likely to subvert physiological functions, which go far beyond the immune system, possibly affecting tumor progression as demonstrated by the opposing effects of nandrolone and p,p′DDE on THP-1 cell proliferation." (PMID 28684670, 2017). "Moreover, inhibition of RACK1 expression using siRNA was shown to reduce the tumorigenicity of MeWo in a xenograft tumor model." (PMID 18442364, 2008). "Therefore, RACK1 content in mouse tumor tissues was also detected in our experiment." (PMID 39251538, 2024). "Therefore, we speculated that Bacteroides fragilis might regulate the content of RACK1 protein in tumor tissues by down-regulating the level of IBA in tumor-bearing mice." (PMID 39251538, 2024). "Moreover, the RACK1 could rescue tumor weight and size respectively; these parameters were both suppressed by the overexpression of circVPRBP." (PMID 36658304, 2023). "Moreover, there are also some conflicting reports on the role of RACK1 in tumor progression." (PMID 37848434, 2023). "Meanwhile, Rack1 deficiency did not cause significantly increased cell death owing to apoptosis or autophagy analysis, but dramatically reduced the proliferation of MB tumor cells." (PMID 34480519, 2021). "RACK1 inhibition may be important for rolB-mediated tumor progression in plants." (PMID 29396465, 2018). "However, H1339 and EPLC-272H tumor cells express similar amounts of RACK1 and also sequence analysis did not reveal any mutations in the PAS-A domain of HIF-1α in H1339 cells." (PMID 22347438, 2012). "Our group and others have successfully identified novel apoptotic controlling genes including LUCA15/RBM5 a novel tumor suppressor gene, fau (Finkel–Biskis–Reilly murine sarcoma virus (FBR-MuSV) associated ubiquitously expressed gene), vATPase, protein phosphatase 4 (PP4), Toso and RACK-1." (PMID 19698770, 2009). "Described as a partner for RACK1 and intersecting with the HSP70 interactome protein K2C1 completes the linking of the PKC-RACK1 complex with tumor cell migration through the ITGB1 molecular environment." (PMID 41369326, 2025). "Studies have shown that the expression of RACK1 is related to EMT and can promote the invasion and metastasis of tumour cells." (PMID 41190648, 2025).